IL6 (interleukin 6)
Diseases named in the same sentence as IL6 in open-access papers (continued):
Sharing a sentence is not in itself a finding about the gene and the disease.
type 2 diabetes (continued). "The trial found an increased risk of type 2 diabetes with higher concentrations of CRP and IL-6." (PMID 38730445, 2024). "Elevated circulating levels of IL-6 are an independent predictor of type 2 diabetes development." (PMID 36769472, 2023). "Two clinical studies reported increased serum levels of anti-inflammatory cytokines (IL-4 and IL-10) and decreased levels of TNF-α, IFNγ, IL-12, and IL-6 in females with type 2 diabetes who received 8 weeks of daily NUTRIOSE® supplementation (10 g/day) versus baseline levels." (PMID 37836513, 2023). "In a meta-study examining 15 reports of 5421 total cases of type 2 diabetes, IL-6 was strongly related, a finding supported by a subsequent multi-ethnic analysis of 260,614 diabetics which found that Asp358Ala mutations in the IL-6 receptor (IL-6R) were correlated with type 2 diabetes." (PMID 36143948, 2022). "In addition, these chronic inflammatory markers (IL-6, CRP, and TNF-alpha, among others) are associated with several different diseases, including infection, cardiovascular disease, and type 2 diabetes mellitus (T2DM)." (PMID 35053667, 2022). "In the case of IL-6, the plasma level of IL-6 increased in type 2 diabetic patients." (PMID 35204193, 2022). "IL-6 then activates the STAT3/SOCS3 pathway in the liver, resulting in decreases in the expression of GLUT2 and GLUT4 in hepatocytes, which is the cause of type 2 diabetes." (PMID 34576053, 2021). "Furthermore, IL-6 has been suggested to contribute to the development of type 2 diabetes, and intervention studies identified IL-6 as a key regulator of muscle mass during cachexia." (PMID 34707570, 2021). "Regarding peripheral biomarkers associated to neuropathy, some of those are related to chronic inflammatory state such as the inflammatory cytokine IL-6, and to the innate immune response receptor TLR4 associated more frequently to the severity of neuropathy in type 2 diabetes patients." (PMID 33810048, 2021). "Additionally, plasma levels of C-reactive protein (CRP), tumor necrosis factor-α (TNF-α), and interleukin-6 (IL-6) are elevated in subjects with type 2 diabetes, indicating the existence of low-grade systemic and hyperglycemia-induced inflammation." (PMID 33536442, 2021). "In addition, the risk of developing type 2 diabetes was highest among subjects with elevated IL-18 and CRP or IL-18 and IL-6, respectively." (PMID 34829612, 2021). "If so, then blocking IL-6 mediated inflammation via the IL6R may help prevent or treat type 2 diabetes." (PMID 33096487, 2020). "Chronic inflammation, which is partly mediated via the interleukin 6 (IL-6) pathway, has been hypothesized to play a critical role in the pathophysiology of type 2 diabetes (T2D)." (PMID 33096487, 2020). "Hesperidin and naringin lowered the level of pro-inflammatory cytokine (tumor necrosis factor-alpha (TNF-α) and interleukin (IL)-6) production and enhanced antioxidant defenses in a type 2 diabetes rat model by normalizing the altered blood glucose and antioxidant parameters in the liver." (PMID 32977511, 2020). "Our findings indicate that suppression of Aurora-A could at least partially enhance insulin sensitivity by decreasing the number of infiltrating macrophages and IL-6 level in a type 2 diabetic mouse model." (PMID 33043822, 2020). "Male Wistar rats, fed with a high-fat diet and treated with a low dose of STZ (30–40 mg/ kg body weight) is reported to be a reliable model for human type 2 diabetes symptoms, which include peripheral insulin resistance, increased plasma interleukin-6 (IL-6) and hyperglycemia." (PMID 32282828, 2020). "For instance, eight weeks of 84% dark chocolate supplementation along with therapeutic lifestyle changes guidelines reduced inflammatory markers (high-sensitivity C-reactive protein (hs-CRP), tumor necrosis factor-alpha (TNF-α), and interleukin-6 (IL-6)) in type 2 diabetic patients." (PMID 33007981, 2020).
type 2 diabetes (continued). "Interleukin-6 shows considerably more variability in people with type 2 diabetes, however this was found to be only in samples taken in the afternoon suggesting that there may be some diurnal variation in people with type 2 diabetes." (PMID 32693740, 2020). "After 30 days of treatment, B. vernae extract significantly decreased the serum levels of fasting blood glucose, insulin, insulin resistance index, glycated serum protein, TNF-α, IL-1β, and IL-6, whereas significantly increased the serum levels of insulin sensitivity index in type 2 diabetic rats." (PMID 32636751, 2020). "In addition, a significant correlation was reported between IL-6 and worse survival in metastatic breast cancer patients and between BMI and IL-6 levels in patients with type-2 diabetes." (PMID 31443251, 2019). "After the identification of the improving effect of JQJT tablets on the gut barrier, since insulin resistance was closely related to the low level inflammatory response in type 2 diabetes we evaluated the effect of JQJT tablets on inflammation by checking the levels of IL-6, TNF-α, and MCP-1." (PMID 30733971, 2019). "Pro-inflammatory molecules (e.g., TNF, IL-6, IL-1β) are increased in type II diabetes and AD, which may compromise the hippocampal insulin receptor expression and/or signaling." (PMID 31291963, 2019). "Type 2 diabetes (T2DM) and its complications are associated with a systemic low-grade inflammation manifested by higher systemic levels of proinflammatory cytokines, such as IL-6, IL-1β, or TNFα." (PMID 30983877, 2019). "Indeed, elevated CRP and IL-6 independently predicted the development of type-2 diabetes across a 4-year period in the Women's Health Study, after controlling for BMI and family history of type-2 diabetes." (PMID 30538987, 2018). "The efficiency of serum IL-6 levels for the discrimination of infected and noninfected ulcer in infections of ulcers associated with type 2 diabetes was shown for the first time in our study." (PMID 29675434, 2018). "In vitro IL-6 induced insulin resistance which support its role in type 2 diabetes occurrence." (PMID 28484449, 2017). "Moreover, via upregulation of IL-6 and osteopontin, TLR2 causes impaired insulin-mediated brain activities, which are an early step in the development toward type 2 diabetes." (PMID 28536605, 2016). "An increased IL-6 level was also observed in patients with type 2 diabetes." (PMID 27965984, 2016). "In examinations concerning the concentrations of pro-inflammatory markers in patients suffering from type 2 diabetes, significantly higher concentrations of IL-6, CRP, and fibrinogen were demonstrated in the case of the co-occurrence of PAD than without this disease." (PMID 27834825, 2016). "In addition, a previous study showed that pterocarpan-enriched soy leaf supplementation led to inhibiting the gene expression of TNF-α and IL-6 in the white adipose tissue in type 2 diabetic mice." (PMID 27869712, 2016). "Moreover, A-FABP was found to be associated with several variables including HbA1C, BMI, TG, HDL-C, HOMA-IR, WHR, CRP, and IL-6 in obese subjects with type 2 diabetes." (PMID 27819006, 2016). "Furthermore, IL-6 level has been found to predict worse cognitive performance in Digit Symbol Coding test in the elderly and type 2 diabetes elders." (PMID 25214388, 2015). "Studies have shown that CRP, IL-6, and other cytokines mediate insulin metabolic pathways, weaken insulin receptor signal transduction, induce disorders of glucose metabolism, and stimulate type 2 diabetes." (PMID 25132859, 2014). "Similarly, patients with T2D show increased systemic levels of IL-6 and islets isolated from type 2 diabetic animal models produce increased amounts of IL-6." (PMID 24594974, 2014). "In regards to the functional polymorphism rs1800796 in the IL-6 gene, it was only found to be associated with risk of type 2 diabetes, but not with coronary heart disease." (PMID 24984610, 2014).
type 2 diabetes (continued). "Reduction of IL-6 expression might prevent or ameliorate the pathogenesis of cancer, type 2 diabetes, and cardiovascular disease." (PMID 24124509, 2013). "Individuals with type 2 diabetes had the most pronounced IL-6 and IL-10 elevations." (PMID 24555158, 2013). "However, data evaluating IL-6’s long term ability to predict clinical outcomes in people with type 2 diabetes is scarce." (PMID 23987834, 2013). "Our aim with this study was to investigate whether IL-6 signaling is affected in skeletal muscle or in satellite cells of people with type 2 diabetes." (PMID 22761857, 2012). "Levels of inflammation in type 1 and type 2 diabetes are still unknown, but it has been found that plasma levels of IL-6 correlate with C-peptide levels and insulin sensitivity." (PMID 22547909, 2012). "Reduced antioxidant defences in type 2 diabetes result in increased oxidised LDL which promotes increased synthesis of proinflammatory cytokines interleukin-6 (IL-6) and tumour necrosis factor alpha (TNF-α), major and minor modulators, respectively, of blood plasma c-reactive protein (CRP) levels." (PMID 23094144, 2012). "Participants who developed type 2 diabetes had higher baseline IL-6 levels than participants who did not, but the association was no longer significant after multivariate adjustment, a finding also reported by others." (PMID 23251619, 2012). "We now report a sub-study of the parent study, where our current goal is to simultaneously measure the changes in plasma hsCRP, TNF-α and interleukin-6 after a mixed-meal breakfast in patients with Type 2 diabetes and relate these changes to those of post-meal glucose, insulin and triglycerides." (PMID 21517955, 2011). "Furthermore, plasma levels IL-6 levels were increased in patients with type 2 diabetes, and increased IL-6 levels were predictive of the development of type 2 diabetes." (PMID 21960997, 2011). "In addition, increased levels of CRP, and its inducer interleukin-6 (IL-6), are predictive of the development of type 2 diabetes in various populations." (PMID 21960997, 2011). "Furthermore, elevated IL-6 levels predicted the development of type 2 diabetes in a prospective case-control study, supporting a possible role for inflammation in diabetogenesis." (PMID 21122092, 2010). "One can speculate that, childhood filarial infection reduces TNF-α, IL-6 and GM-CSF levels thereby conferring protection against type-2 diabetes." (PMID 20559443, 2010). "Furthermore, adiponectin is inversely related to various inflammatory markers such as tumour necrosis factor-α (TNF-α), C-reactive protein (CRP) and interleukin-6 (IL-6) in normal subjects and patients with type 2 diabetes and CVD." (PMID 20066136, 2008). "Finally, results of the population study from the European Prospective Investigation into Cancer and Nutrition Potsdam indicated a significant interaction between plasma IL-1β, IL-6 and type II diabetes development." (PMID 15904534, 2005). "On the other hand, the benefits of IL-6 inhibitors appear to extend to improved control of glucose and HbA1c levels in RA patients with type 2 diabetes mellitus (T2DM)." (PMID 40648921, 2025). "For instance, they interact with CD11c+ cells, leading to elevated IL-6 production in the lungs during Mtb infection, particularly in type 2 diabetes mellitus (T2DM) contexts." (PMID 40825006, 2025). "Serum levels of IL6 from Emirati patients with type 2 diabetes (T2D) were measured, and the effect of antidiabetic drugs on IL6 levels was studied." (PMID 38667300, 2024). "Interleukin 6 (IL-6) isa pro inflammatory cytokine, the presence of IL-6 is normal in tissues with normal conditions whereas, in abnormal conditions it leadsto inflammation due to irregular production and over exposure, in-case of Type 2 Diabetes Millets (T2DM) it leads to resistance towardsinsulin." (PMID 37808375, 2023). "Therefore, CTRP12, SFRP5, and IL-6 could be biomarkers for monitoring inflammation, type 2 diabetes, and dyslipidemia." (PMID 37542207, 2023).
type 2 diabetes (continued). "This study aimed to evaluate some immune and inflammatory parameters in HIV and type 2 diabetes (T2D) co-morbidity: Immunoglobulin M and G (IgM and IgG), Interleukin-6, CD4+ T-cells and C-reactive protein." (PMID 37545969, 2023). "Moreover, a dysregulated immune system in patients with type 2 diabetes and chronic inflammation accompanied with elevated cytokine levels such as interleukin-6, tumor necrosis factor-α, and C-reactive protein could promote CRC tumorigenesis." (PMID 39131121, 2022). "Patients with type 2 diabetes mellitus (T2DM) also showed significantly elevated serum CML and hs-CRP with a remarkable increase in TLR-4 expression and IL-6 and TNF-α, suggesting that high level of CML is associated with pro-inflammatory cytokines." (PMID 36077532, 2022). "Studies have indicated that myosteatosis is associated with insulin resistance, type 2 diabetes mellitus (T2DM), dyslipidemia and cardiometabolic diseases, and there was also a link between skeletal muscle density and biomarkers of inflammation, such as CRP, IL-6, TNF-α, adiponectin and leptin." (PMID 35837298, 2022). "IL-6 action is, in part, regulated by variants of IL-6 and IL-6α receptors and contributes to (but is probably neither necessary nor sufficient) for the development of Type 2 diabetes." (PMID 35330193, 2022). "In our cohort, sensitivity and specificity analyses indeed suggest that the combination of CATi and IL-6 may be a more sensitive and specific predictor of severe outcome in patients with type-II diabetes than when these imaging and inflammation parameters are considered individually." (PMID 34384426, 2021). "This further supports the molecular mechanisms behind IL-6-mediated insulin secretion via glucagon-like peptide 1 (GLP-1) contributing to type 2 diabetes (T2D) pathophysiology." (PMID 33517400, 2021). "Regarding serum levels comparison within the different groups, increased levels of IL-6 were noted in patients with neural pain secondary to leprosy and type II diabetes mellitus in combination with neuropathic pain, indicating that IL-6 may be a pain biomarker." (PMID 32038662, 2020). "Evidence from animal models and observational epidemiology points to a role for chronic inflammation, in which interleukin 6 (IL-6) is a key player, in the pathophysiology of type 2 diabetes (T2D)." (PMID 33096487, 2020). "Because PA induces secretion of IL-6 from macrophages and our data demonstrates PA induces secretion of IL-1β from human MoDCs, it is possible to suggest that PA may exacerbate the development of type 2 diabetes through stimulation of innate immune cells." (PMID 28463985, 2017). "Furthermore, it has been reported that the increase in pro-inflammatory cytokines such as interleukine-1 (IL-1), tumor necrosis factor alpha (TNF-α) and interleukin 6 (IL-6) in a type 2 diabetic state is commonly accompanied by a decrease in cellular antioxidant levels and increased apoptosis." (PMID 28933769, 2017). "Among subjects at higher risk of type 2 diabetes, an acute postprandial intervention of MUFA breakfast (72 E%) containing macadamia nut oil showed that several inflammatory genes were upregulated in subcutaneous adipose tissue (MCP-1, IL-1β, IL-6, IL-6R, TNF-α and TNFRSF1A)." (PMID 28076613, 2017). "IL-6 in itself may be related to the development of type 2 diabetes." (PMID 26911440, 2016). "Further, overproduction of IL-6 and MCP-1 by inflamed adipocytes could be directly linked with development of type 2 diabetes in obese patients where the paracrine action of MCP-1 decreases PPARγ expression thus leading to enhanced insulin resistance of adipocytes." (PMID 25926797, 2015). "Although they did not detect clear differences in serum omentin-1 levels between type 2 diabetes patient with and without ischemic heart disease, multiple regression analysis showed that IL-6 level was an independent risk factor influencing serum omentin-1 level." (PMID 22108456, 2011).
type 2 diabetes (continued). "Our results corroborate these findings, as both the ART and ART + type II diabetes groups exhibited consistently elevated levels of inflammatory biomarkers, including CRP, IL-6, TNF-α, and fibrinogen, compared to the control group." (PMID 39860995, 2025). "Biomarkers such as TNF-α, CRP, and IL-6 showed strong correlations with nausea, diarrhea, abdominal pain, and bloating, with the most severe symptoms observed in the ART + type II diabetes group." (PMID 39860995, 2025). "Despite limitations, this study demonstrates a distinctive inflammatory tear cytokine profile (elevated IL-6, CXCL8, IL-15, CCL5, VEGF) in type 2 diabetes patients, contrasting with decreased systemic inflammation." (PMID 41030257, 2025). "IL-6 has previously been studied as a predictor of CVD and mortality also in patients with type 2 diabetes." (PMID 39193712, 2025). "NSPT was associated with a significant reduction in high-sensitivity C-reactive protein (hs-CRP) and proinflammatory cytokines (IL-6, TNF-α), as well as with decreased HbA1c levels, particularly in patients with type 2 diabetes." (PMID 40842443, 2025). "Chronic low-grade inflammation in type 2 diabetes activates MAPK signaling and increases cytokines such as TNF-α, IL-6, and IL-8, which enhance thyroid cell proliferation, angiogenesis, and survival, favoring tumor development." (PMID 41515940, 2025). "In those with type 2 diabetes, it was observed that those treated with a GLP-1 agonist had decreased levels of prostaglandin and cytokine interleukin-6 levels." (PMID 39944451, 2025). "This study aims to evaluate the association between glycemic control, inflammatory markers (IL-1β, IL-6, MMP-8), and periodontal health in patients with type 1 and type 2 diabetes." (PMID 40283677, 2025). "In PLWH with MASLD or type 2 diabetes, lipotoxicity, oxidative stress, and activation of the NLRP3 inflammasome amplify the production of inflammatory cytokines (IL-6, TNF-α), with deleterious effects on mitochondrial function and immune homeostasis." (PMID 41153793, 2025). "In a controlled trial involving men with type 2 diabetes, weekly semaglutide administration for 6 months resulted in statistically significant decreases in circulating TNF-α and IL-6, demonstrating direct anti-inflammatory benefits." (PMID 41511355, 2025). "Firstly, it provides new insights into the correlation between elevated inflammatory biomarkers—such as CRP, IL-6, TNF-α, and fibrinogen—and gastrointestinal symptoms in HIV-positive patients on ART, particularly those with type II diabetes." (PMID 39860995, 2025). "In patients with type 2 diabetes, SGLT2 inhibitors decrease the levels of proinflammatory cytokines (TNF-α, IL-6, and IL-1β) and attenuate the activity of NLRP3 inflammasome." (PMID 40004134, 2025). "Elevated levels of pro-inflammatory cytokines, especially IL-6, along with CRP and other markers, are common targets for intervention in managing type 2 diabetes." (PMID 41011276, 2025). "Wang’s animal study stands alone in demonstrating the increased expression of pro-inflammatory cytokines TNF-α, IL-6 and IL-1β and the decreased expression of anti-inflammatory cytokines IL-4 and IL-10 in the midbrain of MPTP-treated type 2 diabetic mice." (PMID 40672460, 2025). "Previous studies have reported that cold exposure increases systemic inflammatory cytokines such as IL-1β, IL-6, and TNF-α in patients with type 2 diabetes." (PMID 40270542, 2025). "Twelve weeks of HIIT lower IL-6 and TNF-α in obese adolescents and type 2 diabetes patients, while enhancing IL-10 secretion to support anti-inflammatory capacity." (PMID 40777031, 2025). "The connection between well-known inflammatory markers such as C-reactive protein (CRP), IL-6, IL-8, TNF-α, and endothelin-1 and DAN has been established in patients with type 1 and type 2 diabetes." (PMID 40137134, 2025).